PCDHAC2 (protocadherin alpha subfamily C, 2)
Description:
Potential calcium-dependent cell-adhesion protein. May be involved in the establishment and maintenance of specific neuronal connections in the brain.
Synonyms: PCDH-alpha-C2
Tractability: Antibody: its Gene Ontology location is reachable by antibodies, with high confidence; UniProt places it where antibodies can reach, with medium confidence; UniProt predicts a signal peptide or a membrane-spanning region. PROTAC: ubiquitination databases record sites on it; its protein half-life has been measured.
Gene: Protein-coding gene on chromosome 5 (140,966,470 to 141,012,347, forward strand). Ensembl gene ENSG00000243232.
Subcellular location: Cell membrane
Subcellular location (Human Protein Atlas): Nucleoplasm; Mitochondria
Gene Ontology:
Molecular function: cell adhesion molecule binding; calcium ion binding
Biological process: cell adhesion; nervous system development; homophilic cell-cell adhesion
Cellular component: plasma membrane; membrane
Genetic constraint (gnomAD): Loss-of-function variants: 22 observed, 63.34 expected, observed/expected ratio (o/e) 0.35, 90% interval 0.25 to 0.5. The upper end of that interval is the gene's LOEUF score, 0.5, which puts it in group 2 of 6, group 1 being the genes least tolerant of losing a copy. Missense variants: 1,130 observed, 1,291.9 expected, observed/expected ratio (o/e) 0.87, 90% interval 0.83 to 0.92. Synonymous variants: 539 observed, 528.91 expected, observed/expected ratio (o/e) 1.02, 90% interval 0.95 to 1.09.
Homologues: Orthologues: chimpanzee PCDHA2 (99% identical), macaque PCDHAC2 (99% identical), rabbit PCDHAC2 (95% identical), pig PCDHAC2 (94% identical), mouse Pcdhac2 (93% identical), tropical clawed frog pcdhac2 (62% identical), zebrafish pcdh2ab9 (51% identical), zebrafish pcdh2ac (51% identical). Paralogues in human: PCDHAC1 (47% identical), PCDHA8 (45% identical), PCDHA2 (44% identical), PCDHA6 (44% identical), PCDHA1 (44% identical), PCDHA5 (44% identical), PCDHA11 (43% identical), PCDHA3 (43% identical), PCDHA4 (43% identical), PCDHA12 (43% identical), PCDHA7 (43% identical), PCDHA13 (43% identical), and 49 more.
Diseases named in the same sentence as PCDHAC2 in open-access papers:
PCDHAC2 is named in the same sentence as 7 diseases in open-access papers, as found by Europe PMC text mining. Sharing a sentence is not in itself a finding about the gene and the disease. The quoted sentences say what the papers report.
colorectal cancer (1 paper, 2022). A primary or metastatic malignant neoplasm that affects the colon or rectum. "A functional role for the hypermethylation and gene silencing of PCDHαβγ family genes (PCDHAC2, PCDHB7, PCDHB15, PCDHGA1 and PCDHGA6) was also identified recently in colorectal cancer influencing the WNT/B-catenin pathway implicated in proliferation, survival and migration." (PMID 36443814, 2022).
pancreatic adenocarcinoma (1 paper, 2019). "An exploratory study of methylation analysis on PCDHAC2, PCDHGC5 and PCDH10 was carried out in 11 pancreatic adenocarcinomas." (PMID 31088413, 2019).
cancer (5 papers, 2016 to 2022). A tumor composed of atypical neoplastic, often pleomorphic cells that invade other tissues. "We also detected another five smRMGs that mutated in nearly half of the samples in corresponding cancers, including PCDHAC2 in SKCM (53%), ZFPM1 in ACC (52%), VHL in KIRC (49%), GNAQ in UVM (49%), and ADAM6 in LUSC (45%)." (PMID 30107644, 2018). "The largest FMGS identified in all these cancer stages contained 8 genes (k = 8; RP1, PCDHAC2, TENM3, SPHKAP, ODZ3, ADAMTS18, SCN5A, PKHD1L1) found in SKCM-stage IV." (PMID 27556693, 2016). "Furthermore, methylation patterns in SDMCs influenced the transcription of several genes (MEIS1, MIA3, PCDHAC2, SH3BP4, and ATP8B1) involved in well-known cancer-related pathways and cancer hallmarks (FDR < 0.05)." (PMID 36348462, 2022). "PCDHGC5, PCDHAC2, SPTA1, XIRP2 and FLG seemed unrelated with cancer based the reference study." (PMID 27835590, 2016). "Notably, the methylation status of PCDHAC2 and PCDHGC5 were never analyzed before in PDAC, while PCDH10 had been previously studied in PDAC cancer cell lines and one study analyzed this gene in PDAC primary tumors." (PMID 31088413, 2019).
PCDHAC2 also shares sentences with these, for which no sentence is quoted: tumor (3 papers); cervical cancer (1); communicating hydrocephalus (1); kidney tumor (1).